CRP (C-reactive protein)
Diseases named in the same sentence as CRP in open-access papers (continued):
Sharing a sentence is not in itself a finding about the gene and the disease.
cardiovascular disease (continued). "C-reactive protein (CRP) is a sensitive marker for acute inflammatory response and an independent risk factor for cardiovascular disease." (PMID 34941184, 2021). "Clinical data indicate that patients with C-reactive protein (CRP) levels higher than 2 mg per liter suffer from persistent inflammation, which is associated with high risk of cardiovascular disease (CVD)." (PMID 33803115, 2021). "Lipoprotein(a) [Lp(a)] and high-sensitivity C-reactive protein (hs-CRP) levels are associated with cardiovascular disease (CVD) in the general population, even after adjusting for conventional CVD risk factors." (PMID 33299770, 2020). "Non-HDL cholesterol, apolipoprotein A-I and B100, standard lipid measures, lipid ratios, and CRP as risk factors for cardiovascular disease in women." (PMID 33027378, 2020). "This prolonged state of chronic inflammation with increased levels of C-Reactive Protein (CRP) is a proven risk factor for cardiovascular diseases." (PMID 33326424, 2020). "The Centers for Disease Control and Prevention and the American Heart Association (AHA) also suggested that CRP is one of the strongest predictors of cardiovascular disease." (PMID 32355581, 2020). "In the current trial, participants in the EX-LC group demonstrated a greater reduction in inflammation documented by plasma concentrations of CRP, a marker associated with cardiovascular disease risk." (PMID 32075010, 2020). "This evidence has led to the development of a high sensitivity CRP assay which can accurately measure CRP levels <3 mg/L and assess an individual's risk of developing cardiovascular disease." (PMID 32117266, 2020). "C-reactive protein is not only an inflammatory biomarker but also an important risk factor associated with ageing-related diseases including cardiovascular disease." (PMID 32544081, 2020). "Of the wide array of inflammatory biomarkers that have been studied, high‐sensitivity C‐reactive protein (hs‐CRP) has received the most attention for its use in screening and risk reclassification of cardiovascular disease." (PMID 32458487, 2020). "In this regard, cortisol or further inflammatory risk markers such as C-reactive protein are important factors associated to cardiovascular disease." (PMID 32722703, 2020). "Alkaline phosphatase is already one of the risk factors or treatment target for cardiovascular disease in addition to the highly sensitive C-reactive protein as atherosclerotic biomarkers." (PMID 32825442, 2020). "In the 70-person cohort, 56% of participants who were at high risk for cardiovascular disease, based on hs-CRP level >5, lowered that risk." (PMID 32983729, 2020). "CRP has been recognized as a relevant prognostic risk factor for cardiovascular disease, especially in association with abdominal obesity." (PMID 33082492, 2020). "Biomarkers of chronic inflammation (such as C-reactive protein) have long been associated with cardiovascular disease and mortality; however, biomarkers involved in antiviral cytokine induction and adaptive immune system activation remain largely unexamined." (PMID 32240245, 2020). "Coronary artery calcium provides superior discrimination and risk reclassification of cardiovascular disease in intermediate-risk individuals, compared with ankle-brachial index, high-sensitivity CRP and family history." (PMID 33326424, 2020). "Plasma mannose levels have been tightly associated with atherogenesis, cardiovascular diseases, and mortality, and indirectly also with markers of inflammation (including CRP), creatinine, lower glomerular filtration rate, and with urine albumin excretion." (PMID 33187152, 2020). "CRP has also been considered a significant risk factor for many systemic diseases, such as cardiovascular disease and type 2 diabetes." (PMID 32994872, 2020). "IL-6 is a key inflammatory factor whose secretion is activated by the C-reactive protein and has been implicated in the pathogenesis and clinical evolution of cardiovascular diseases." (PMID 32455143, 2020).
cardiovascular disease (continued). "Pariapical lesions also associated with CRP levels >3 mg/L (OR = 4.0), supporting a mechanistic link for cardiovascular diseases in young adults." (PMID 32388515, 2020). "The blood levels of acute phase proteins Serum amyloid-A (SAA) and C-reactive protein (CRP) are suggested to be predictive of cardiovascular disease risk in humans." (PMID 31477116, 2019). "Another component widely used in clinical practice as a marker of inflammaging is C-reactive protein (CRP), which is produced in response to IL-6 and is also a robust predictor of risk for cardiovascular disease." (PMID 31411315, 2019). "C-reactive protein (CRP) is a marker of subclinical inflammation that has been found to be associated with cardiovascular disease risk." (PMID 31143476, 2019). "Increased levels of acute phase proteins SAA and C-reactive protein (CRP) are associated with increased risk of cardiovascular disease in prospective epidemiological studies." (PMID 31182125, 2019). "High concentrations of CRP level in infant serum can increase the risk of cardiovascular disease in the long term due to CRP level functions to control serum cholesterol level." (PMID 31174304, 2019). "IL-6 also stimulates the production of C-reactive protein (CRP), which is a marker for the evaluation of systemic inflammation and risk of developing cardiovascular diseases." (PMID 31394805, 2019). "It uses genetic variants for exposures [e.g. C reactive protein (CRP)] as instrumental variables and another set of genetic variants from another independent GWAS for the outcomes variants (e.g. cardiovascular disease)." (PMID 30606278, 2019). "Prior studies have shown that HNF1A rs1169288 polymorphism is significantly associated with CRP concentration, cardiovascular diseases, and decreased in vitro transcriptional activity of downstream target gene promoters." (PMID 31915469, 2019). "Several inflammatory markers, including IL-6, C-reactive protein (CRP), and fibrinogen, are established risk factors for cardiovascular disease." (PMID 31165309, 2019). "CRP is recognized by the American Heart Association and the Center for Disease Control as a predictive factor for cardiovascular disease risk." (PMID 29476238, 2019). "It has been demonstrated that inflammatory biomarkers such as C-reactive protein (CRP) are significantly associated with cardiovascular disease." (PMID 33817205, 2019). "Marginal reductions in CRP following mindfulness interventions have, however, been observed among overweight adults at risk for cardiovascular disease and among lonely older adults at risk for all-cause mortality." (PMID 31295270, 2019). "Increased serum levels of C-reactive protein (CRP), an important component of the innate immune response, are associated with increased risk of cardiovascular disease (CVD)." (PMID 31622379, 2019). "High-sensitivity C-reactive protein (hs-CRP) is a common risk factor for developing cardiovascular disease." (PMID 31340788, 2019). "Although CRP response is unspecific and is triggered by many disorders unrelated to cardiovascular disease, mathematical models that incorporate high-sensitivity CRP (hsCRP) improve CV risk prediction." (PMID 29552019, 2018). "The American Heart Association and the Center for Disease Control and Prevention determined that cardiovascular diseases risk differ depending on CRP concentration." (PMID 29597295, 2018). "In other studies, sub-clinical CRP has been associated with increased risk of cardiovascular disease-related mortality in healthy subjects." (PMID 30123515, 2018). "Considering the fact that low-grade systemic inflammatory state, with an increase in the concentration of CRP as a marker is a risk factor for cardiovascular diseases." (PMID 30026764, 2018). "Magnesium supplementation reduces plasma C-reactive protein (CRP) concentrations in those with levels > 3 mg/dL, which is indicative of inflammation and an increased risk for cardiovascular disease." (PMID 29799073, 2018).
cardiovascular disease (continued). "Given the known close relationship between a high CRP and risk of cardiovascular disease, it is possible that accelerated atheromatous disease is part of the metastatic process and accompanies progressive disease." (PMID 30138391, 2018). "The Framingham Study also showed that serum GGT was positively associated with incident cardiovascular disease even after accounting for CRP." (PMID 30245751, 2018). "CRP has been regarded as an emerging risk factor for the development of cardiovascular diseases that involve systemic inflammation (Singhet al., 2008)." (PMID 30918627, 2018). "Consumption of bilberry juice by patients with an increased risk for cardiovascular disease led to decreased plasma concentrations of CRP, IL-6 and IL-15." (PMID 30307962, 2018). "Aside from acting as a potential biomarker for cardiovascular disease, there is now a wealth of experimental data suggesting a direct causative role for CRP in promoting cardiovascular disease." (PMID 29946323, 2018). "An avalanche of epidemiological and experimental observations followed, purporting to show that CRP is a pro-atherogenic risk factor for cardiovascular disease." (PMID 30459761, 2018). "In this study, GDF15 was modestly correlated with and additive to CRP in identifying those at risk for cardiovascular disease events." (PMID 29967567, 2018). "Although serum CRP levels have gained greater importance as a risk marker in cardiovascular disease (CVD), the magnitude of its risk potential has been debated." (PMID 30154790, 2018). "C-reactive protein is a risk marker for cardiovascular disease, which also features an important function in the inflammatory process, especially in the acute phase, when CRP can increase up to 1000 times its normal serum level." (PMID 30510801, 2018). "Average C-reactive protein levels of 3.2 mg/L indicated intermediate risk for cardiovascular disease." (PMID 30249576, 2018). "High-sensitivity assays, such as nephelometric assays, are used to detect baseline levels of CRP and patients who are at risk of cardiovascular disease." (PMID 29706967, 2018). "It is known that cardiovascular diseases and related acute-phase reactions with elevated levels of CRP and SAA share various common risk factors involving smoking, high BMI, and older age." (PMID 29742255, 2018). "We also found elevated CRP and fibrinogen levels in the retinopathy group, suggesting increased inflammation and cardiovascular disease risk." (PMID 28616394, 2017). "The lower CRP after training is considered important, since high CRP levels are strongly associated to the incidence of cardiovascular disease." (PMID 29016675, 2017). "In conclusion, the pathogenic role of CRP in cardiovascular diseases has been well established, but its effects on renal injury are relatively understudied." (PMID 28886014, 2017). "Markers of systemic inflammation such as C-reactive protein (CRP) are elevated in subjects at risk for cardiovascular disease (CVD) but lack the specificity required for reliable differentiation between lesions from symptomatic and asymptomatic patients." (PMID 28319050, 2017). "Among novel cardiovascular disease risk factors,C-reactive protein was 3.3% (95% CI 1.0–5.6%) higher, interleukin-6 was 2.7%(95% CI 1.1–4.3%) higher, and vitamin D was 11.2% (95% CI 1.0–20.4%)lower." (PMID 27899528, 2017). "Although this marker is considered one of the main factors related to the inflammatory process, in which elevated CRP levels are associated with mortality and cardiovascular disease in CRD patients, the results in the literature are contradictory." (PMID 28473854, 2017). "C reactive protein (CRP), an acute phase protein and cardiovascular disease risk marker, triggers other detrimental cardiovascular outcomes such as increased clotting, generation of oxygen radicals and plaque destabilization." (PMID 28396623, 2017).
cardiovascular disease (continued). "A recent study found close correlation between CRP and IL-6 in patients with high risk of cardiovascular disease." (PMID 29143684, 2017). "Inflammatory factors such as C-reactive protein, tumor necrosis factor-α and interleukin-6 have all been associated with an increased risk of cardiovascular disease." (PMID 27483308, 2016). "Prolonged inflammation and elevated plasma CRP concentrations have been implicated with cardiovascular disease and other common causes of morbidity." (PMID 27386859, 2016). "C-reactive protein (CRP) is positively correlated with cardiovascular disease risk, and our previous study demonstrated that it induces inflammatory reactions of perivascular adipose tissue by targeting adipocytes." (PMID 27526687, 2016). "Romero‐Corral and colleagues 21 stated that such interaction occurs when assessing cardiovascular disease, resulting in a weaker association between CRP and cardiovascular disease after adjustment for leptin." (PMID 26632325, 2016). "Serum levels of the acute phase proteins SAA and CRP are known risk factors for cardiovascular disease in prospective studies." (PMID 26792395, 2016). "Our results are in line with these data, since we show a significant positive association between CRP levels and risk of all cause and cardiovascular disease mortality." (PMID 27311068, 2016). "CRP has been shown to be one of the acute-phase reactants underlying systematic inflammation, and that CRP exists predictive value for cardiovascular disorder or risk factors in healthy subjects." (PMID 27654253, 2016). "Directly after weight loss, SAA1 and CRP, two prominent risk markers for cardiovascular disease, showed median decreases of 43% and 35%, respectively." (PMID 28007936, 2016). "CRP is easily measured and is a significant predictor of risk for serious physical conditions like cardiovascular disease." (PMID 27493807, 2016). "Several inflammatory markers, such as interleukin-6, C-reactive protein (CRP), and fibrinogen, are established risk factors for cardiovascular disease." (PMID 26875192, 2016). "The risks of dying from cardiovascular disease and all causes were consistently higher with increased CRP, AGC and G/L ratio." (PMID 27294662, 2016). "Baseline circulating concentrations of CRP are significantly associated with cardiovascular disease risk in the general population." (PMID 27526687, 2016). "Considering the prognostic utility of CRP, it was used successfully for assessing response to antibiotics, risk stratification of cardiovascular disease and for predicting acute brain dysfunction in critically-ill patients." (PMID 28469676, 2016). "C-reactive protein (CRP), an acute-phase protein associated in observational studies with cardiovascular disease (CVD) risk, provides an illustrative example." (PMID 27342221, 2016). "Subjects in this study were healthy with a mean baseline CRP of 1.5 mg/L, well below the cut off of 3.0 mg/L for of cardiovascular disease risk." (PMID 26404365, 2015). "In particular, elevated concentrations of C-reactive protein (CRP) have been consistently associated with increased risk for cardiovascular disease." (PMID 25874126, 2015). "In the present study, mean baseline CRP levels for each group ranged from 3.10 to 5.47 mg/L, which is above the 3.0 mg/L threshold for high relative risk of cardiovascular disease." (PMID 25951857, 2015). "Living close to busy traffic was associated with increased CRP concentrations, a known risk factor for cardiovascular diseases." (PMID 25816055, 2015). "Although at the current moment it is reasonable to consider CRP as a pro-inflammatory mediator of various chronic diseases, future clinical trials using CRP inhibitors are needed to confirm a causative role between CRP and cardiovascular disease." (PMID 26106588, 2015). "Studies have also compared with other commonly used markers of cardiovascular disease risk such as Carotid intima-media thickness and highly sensitive C-reactive protein." (PMID 25807266, 2015).
cardiovascular disease (continued). "An example from the medical literature is the research about the association of CRP and cardiovascular disease." (PMID 26159541, 2015). "C-reactive protein (CRP) not only serves as one of the most widely known biomarkers of cardiovascular disease and underlying inflammation but also promotes activation of endothelial cells and monocytes, leading to vascular remodeling." (PMID 26557868, 2015). "Alkaline phosphatase is an inflammatory mediator like C-reactive protein (CRP) (a novel risk marker for cardiovascular disease)." (PMID 26167920, 2015). "Human C-reactive protein (CRP) is a homopentameric oligoprotein, which has been validated as a powerful predictor and risk factor of inflammation and cardiovascular disease." (PMID 26610462, 2015). "C-reactive protein (CRP) is a well-known marker of whole body systemic low-grade inflammation and data suggest that CRP is implicated in the development of cardiovascular disease." (PMID 26075745, 2015). "The circulating level of CRP is commonly used as an inflammatory marker to assess the risk for cardiovascular disease (CVD) and stroke." (PMID 25861161, 2015). "Minimal variation in laboratory data was observed in our study group, with the exception of albumin which is a recognized predictor of survival in elderly patients and CRP which is a risk factor for cardiovascular disease." (PMID 26289439, 2015). "Interleukin- 6 (IL-6) is inflammatory markers that the main its effects is the induction of hepatic CRP production which to be an independent, major risk factor for cardiovascular disease." (PMID 26153197, 2015). "In one study enrolling solely adult males, serum total OCN was inversely associated with CRP in those with risk factors for cardiovascular diseases, but the significant association disappeared after adjusting fasting glucose and free fatty acid." (PMID 26578821, 2015). "MR methods have been used previously to investigate the role of high-density lipoprotein and C-reactive protein in predisposition to cardiovascular disease, and have provided strong evidence that PCSK9 inhibition prevents cardiovascular disease." (PMID 26305103, 2015). "CRP is the most frequently measured inflammatory marker and is associated with an increased risk of cardiovascular disease and mortality in both the general population and in CKD and ESRD patients." (PMID 26651991, 2015). "Markers of inflammation are elevated in HIV-infected patients, and elevations in markers such as high-sensitivity C-reactive protein, D-dimer, and interleukin-6 (IL-6) have been associated with increased risk for cardiovascular disease." (PMID 25648075, 2015). "CRP as a cardiovascular disease (CVD) risk marker has been in the focus of interest lately, especially with the findings of the JUPITER trial." (PMID 25299074, 2014). "Chronic inflammation, a common disorder in patients on hemodialysis which represented by increased C-reactive protein, is the most important cause of cardiovascular disease, and severely linked with morbidity and mortality in these patients." (PMID 24719806, 2014). "CRP < 1.0 μg/mL is generally regarded as low risk, 1.0-2.99 μg/mL as intermediate risk and >3 μg/mL as high risk for the development of cardiovascular disease in subjects apparently free of such disease at baseline." (PMID 25337037, 2014). "CRP has been used to assess inflammation and is also used in a multi-biomarker system as a predictive biomarker for cardiovascular disease risk." (PMID 25587427, 2014). "Altered ABI values were significantly related to family history of cardiovascular disease, CRP, fibrinogen and cardiovascular risk assessed by the NCEP ATP III standard, but not to HIV infection." (PMID 25503743, 2014). "Prospective studies indicate an association between the level of CRP and the long-term risk of cardiovascular disease [9, pages 237–242]." (PMID 25202455, 2014).